UXS1 (UDP-glucuronate decarboxylase 1)
Description:
Catalyzes the NAD-dependent decarboxylation of UDP-glucuronic acid to UDP-xylose. Necessary for the biosynthesis of the core tetrasaccharide in glycosaminoglycan biosynthesis. Catalyzes the synthesis of UDP-xylose in two steps: the hydroxyl group of UDP-glucuronic acid is first oxidized using an enzyme-bound NAD(+) as electron acceptor, favoring the decarboxylation yielding a UDP-4-ketoxylose reaction intermediate and a reduced cofactor NADH bound to the catalytic pocket. In the second step, the 4-keto group is reduced resulting in UDP-xylose and the restoration of the enzyme to its NAD(+)-bound form.
Synonyms: UGD; hUXS; hUXS1; FLJ23591; SDR6E1
Tractability: Small molecule: a structure with a bound ligand is known; it has a binding pocket of medium quality. Antibody: UniProt predicts a signal peptide or a membrane-spanning region. PROTAC: its protein half-life has been measured.
Gene: Protein-coding gene on chromosome 2 (106,093,303 to 106,194,365, reverse strand). Ensembl gene ENSG00000115652.
Subcellular location: Golgi apparatus, Golgi stack membrane; Endoplasmic reticulum membrane
Pathways (Reactome):
Metabolism: Formation of the active cofactor, UDP-glucuronate; Glycosaminoglycan-protein linkage region biosynthesis
Gene Ontology:
Molecular function: identical protein binding; NAD+ binding; protein homodimerization activity; UDP-glucuronate decarboxylase activity
Biological process: glycosaminoglycan biosynthetic process; UDP-D-xylose biosynthetic process; D-xylose metabolic process
Cellular component: catalytic complex; endoplasmic reticulum membrane; extracellular exosome; Golgi apparatus; Golgi membrane; Golgi cisterna membrane
Genetic constraint (gnomAD): Loss-of-function variants: 26 observed, 44.83 expected, observed/expected ratio (o/e) 0.58, 90% interval 0.42 to 0.81. The upper end of that interval is the gene's LOEUF score, 0.81, which puts it in group 3 of 6, group 1 being the genes least tolerant of losing a copy. Missense variants: 383 observed, 469.2 expected, observed/expected ratio (o/e) 0.82, 90% interval 0.75 to 0.89. Synonymous variants: 191 observed, 174.58 expected, observed/expected ratio (o/e) 1.09, 90% interval 0.97 to 1.23.
Homologues: Orthologues: macaque UXS1 (98% identical), chimpanzee UXS1 (98% identical), dog UXS1 (98% identical), mouse Uxs1 (97% identical), guinea pig UXS1 (96% identical), pig UXS1 (96% identical), rat Uxs1 (95% identical), zebrafish uxs1 (86% identical), rabbit UXS1 (84% identical), tropical clawed frog uxs1 (81% identical), Drosophila melanogaster Uxs (62% identical), Caenorhabditis elegans sqv-1 (60% identical). Paralogues in human: TGDS (19% identical), SDR42E1 (19% identical), SDR42E2 (18% identical), GMDS (17% identical), HSD3B1 (17% identical), NSDHL (16% identical), GALE (16% identical), HSD3B2 (16% identical), HSD3B7 (15% identical), GFUS (12% identical).
Diseases named in the same sentence as UXS1 in open-access papers:
UXS1 is named in the same sentence as 9 diseases in open-access papers, as found by Europe PMC text mining. Sharing a sentence is not in itself a finding about the gene and the disease. The quoted sentences say what the papers report.
breast carcinoma (1 paper, 2025). "Notably, recent work has demonstrated that cisplatin-resistant lung and breast cancer cells exhibit sensitivity to UXS1 knockout." (PMID 39886381, 2025).
Catel-Manzke syndrome (1 paper, 2025). Catel-Manzke syndrome is a rare bone disease characterized by bilateral hyperphalangy and clinodactyly of the index finger typically in association with Pierre Robin sequence comprising micrognathia, cleft palate and glossoptosis. "Together, the KI/KO mouse model recapitulates important clinical aspects of Catel–Manzke syndrome, corroborates the biochemical function of TGDS and provides evidence that a functional UXS1 deficiency might underlie the clinical phenotype." (PMID 40836090, 2025). "This work reveals the molecular link between TGDS, UXS1, H6PD and Catel–Manzke syndrome." (PMID 40836090, 2025).
Hepatic fibrosis (1 paper, 2023). The presence of excessive fibrous connective tissue in the liver. "Accordingly, histological hepatic fibrosis was also mitigated by UXS1 knockdown." (PMID 37169760, 2023).
cancer (4 papers, 2021 to 2025). A tumor composed of atypical neoplastic, often pleomorphic cells that invade other tissues. "This underscores the potential of UXS1 as a novel therapeutic target in overcoming chemoresistance in certain cancers, including CRC." (PMID 39886381, 2025). "Interestingly, the survival of cancer cells overexpressing UGDH was shown to be critically dependent on the UDP-glucuronate decarboxylase 1 (UXS1) enzyme that converts toxic UDP-glucuronate to UDP-xylose." (PMID 39456684, 2024). "UDP–GA is processed into UDP–xylose by the enzyme UDP–xylose synthase (UXS1), and when UXS1 is disrupted, UDP–GA selectively accumulates in such cancer cells, poisoning them and disrupting their Golgi structure and function." (PMID 40804482, 2025).
UXS1 also shares sentences with these, for which no sentence is quoted: connective tissue disorder (1 paper); Hepatic steatosis (1); infection (1); lung adenocarcinoma (1); Tumor (1).